E2F3 (E2F transcription factor 3)
Diseases named in the same sentence as E2F3 in open-access papers (continued):
Sharing a sentence is not in itself a finding about the gene and the disease.
cancer (continued). "In accordance with the mRNA expression levels obtained from GEPIA, the protein expression of E2F1, E2F2, E2F3, E2F5, E2F7 and E2F8 were significantly higher in carcinoma tissues." (PMID 32117628, 2020). "The results showed that the mRNA levels of E2F1, E2F2, E2F3, E2F5, E2F7 and E2F8 were significantly lower in adjacent tissues compared with those in carcinoma tissues." (PMID 32117628, 2020). "These include cancer hallmarks of various types: oncogenes (BCL2, BRAF), caspases (CASP6/7), transcription factors (E2F3), cell cycle genes (CDC42, CDK2, CDKN2A), cancer related kinases (JAK2/3, MAPK4/6/14) and DNA repair genes (BRCA1, PARP1 and RAD50)." (PMID 28059167, 2017). "For example, miR‐148a, miR‐34b/c, and miR‐9 downregulate oncogenes, including c‐MYC, E2F3, CDK6, and TGIF2 and are often reduced in cancers." (PMID 28179359, 2017). "Finally, the E2F3- HIF-2α axis could be an important target for cancer intervention." (PMID 28903320, 2017). "Of note, LY6D, ST3GAL4, ASS1, PTP4A3 (also named PRL-3), UBE2C (also named UBCH10), and E2F3 are novel oncogenes and biomarkers whose overexpression are related to metastases, migration, or proliferation of NSCLC and other cancers." (PMID 27935865, 2017). "Furthermore, the link between antioxidant defense and cancer pathology invites future investigation into whether circ_0001741 influences ESCC progression by modulating oxidative stress pathways-a plausible direction given E2F3’s known roles in metabolism and stress responses." (PMID 41372977, 2025). "Given the results of our immune infiltration analysis, we propose that E2F1, E2F2, E2F3, and E2F5 may potentially affect the progression of cancer through anticancer immunity." (PMID 35531101, 2022). "ROC curve analysis of all genes and proteins showed significant high diagnostic performance of miR-34a (AUC = 0.854), MET (AUC = 0.765), and E2F3 (AUC = 0.761) in differentiating between cancer specimens and noncancer tissues." (PMID 29104726, 2017). "Actually, the exact roles of these miRNAs and E2F3 gene in tumorigenesis have not been clearly elucidated in different cancers." (PMID 28947999, 2017). "In conclusion, E2F3 overexpression may transcriptionally upregulate HIF-2α, thus inducing higher cancer malignancy in ccRCC by boosting proliferation, migration, and invasion capacity of cancer cells." (PMID 28903320, 2017). "For us, PTEN and E2F3 downregulation after miR-26a transfection was the most relevant finding because it suggests that this miRNA directly targets genes; this was especially interesting for PTEN as it has proven relevance in cancer processes." (PMID 27517917, 2016). "Specifically, the automated procedure was not able to map some well-known cancer genes, including cyclin-dependent kinase inhibitor 2A (CDKN2A), F-box and WD repeat domain containing 7 (FBXW7), and E2F transcription factor 3 (E2F3), to a hallmark." (PMID 26369414, 2015). "For E2F3, SOX4, CBFB and SMARCC1, the transcript analyses were corroborated by an in-depth IHC analysis not only confirming their increased expression level, but also demonstrating their expression by the cancer cells." (PMID 19156145, 2009). "The generally increased expression of E2F3 and DEK in the cancer tissues may reflect the latter effect, with further increases in individual cases due to deregulation and copy number gains of these genes." (PMID 15876350, 2005).
cancer (continued). "E2F3 interaction with SOX-2, altered its expression levels in TAM resistant cells, and its involvement in regulating pluripotency, differentiation of cancer stem cells (CSC), and the Wnt signaling pathway suggests that it might be involved in the emergence of TAM resistance." (PMID 38864530, 2024). "It is able to target E2F Transcription Factor 3 (E2F3), DNA methyltransferase 1 (DNMT1), met proto-oncogene (MET) and Rapamycin-insensitive companion of mTOR (Rictor) and in EC cells it seems to be down-regulated through CpG hypermethylation, promoting cancer development and progression." (PMID 30037059, 2018). "Quantitative RT–PCR confirmed that the E2F3 transcript level was increased in cancer (2.22-fold, log 2 scale; P=1.26 × 10−7, Student's t-test) and that the average RB1/E2F3 ratio was reduced by −0.87-fold (log 2 scale) from normal mucosa to cancer (P=3.52 × 10−6, Student's t-test)." (PMID 19156145, 2009). "Therefore, the increases in E2F3 and DEK in cultured cancer vs. normal cells may turn out as comparatively moderate." (PMID 15876350, 2005). "E2F3, miR-125a and DKK3 have been reported to be involved in various cancer types, but their detailed roles in GC have not been fully understood." (PMID 31423109, 2019). "For the nine added TF genes, seven of them were reported to take part in apoptosis in various types of cancer or diseases; these seven TFs are STAT3, ETS1, LEF1, STAT4, E2F3, ATF3, and HMGA2, which have not been annotated by GO yet." (PMID 22952919, 2012).
infection (5 papers, 2010 to 2024). The state of being infected such as from the introduction of a foreign agent such as serum, vaccine, antigenic substance or organism. "To address this question, we individually blocked the expression of E2F1, E2F2 or E2F3 with one of two different siRNAs prior to infection with HCMV or transduction with recombinant adenoviruses, and then scored cells for a host DDR by γH2AX immunostaining." (PMID 21589897, 2011). "E2F2 and E2F3 do not influence the infection-associated DDR or viral replication." (PMID 21589897, 2011). "Expression-profiling of Toxoplasma-infected HFFs demonstrated that there are modest increases in the levels of E2F3 (+1.4-fold), c-Myc (+1.9-fold) and E2F1 (+1.5-fold) in Toxoplasma-infected HFFs relative to uninfected HFFs at 24h post-infection." (PMID 20090903, 2010). "The overwhelming majority of changed miRNAs were downregulated after infection and infection plus SP-A2 (1A0) protein rescue, and these were predicted to target genes that play a role in cell cycle and growth and proliferation pathways, such as CCND1, CCND2, CDK7, CDKN2A, E2F1, E2F2, E2F3, and MYC." (PMID 35844510, 2022).
metabolic disease (2 papers, 2023). A congenital disorder (due to inherited enzyme abnormality) or acquired (due to failure of a metabolically important organ) disorder resulting from an abnormal metabolic process. "Overall, these results demonstrate that skeletal muscle–specific loss of E2F3 results in mitochondrial defects that contribute to metabolic disease." (PMID 37395281, 2023).
cardiovascular diseases (1 paper, 2020). "E2F3, a member of the E2F transcription factor family, is closely related to cardiovascular diseases." (PMID 32420356, 2020). "Several studies have also shown that E2F3 is closely related to cardiovascular diseases." (PMID 32420356, 2020).
head and neck tumor (1 paper, 2012). "To further validate the cell line findings of inverse relationship between miR-34a and its target proteins survivin and E2F3, we examined miR-34a, survivin and E2F3 mRNA levels in the primary head and neck tumor samples." (PMID 22629428, 2012).
E2F3 also shares sentences with these, for which no sentence is quoted: chronic myeloid leukemia (3 papers); adenocarcinoma (2); abdominal aortic aneurysm (1); atherosclerosis (1); B cell lymphomas (1); bladder (1); Bloom syndrome (1); brain ischemia (1); Chagas disease (1); cocaine addiction (1); colorectal tumors (1); esophageal cancer (1); Ewing sarcoma (1); head and neck cancer (1); hepatitis B (1); hepatitis C (1); Hirschsprung disease (1); Hodgkins lymphoma (1); Insulin resistance (1); liposarcoma (1); lymph node metastasis (1); malignant peripheral nerve sheath tumor (1); medulloblastoma (1); microcephaly (1); multiple endocrine neoplasia (1); muscle disorders (1); oral squamous cell carcinoma (1); pancreatic adenocarcinoma (1); Pheochromocytoma and Paraganglioma (1); pilocytic astrocytoma (1).
A further 20 diseases each share a sentence with E2F3 in 1 paper.